UGGT2 (UDP-glucose glycoprotein glucosyltransferase 2)
Description:
Recognizes glycoproteins with minor folding defects. Reglucosylates single N-glycans near the misfolded part of the protein, thus providing quality control for protein folding in the endoplasmic reticulum. Reglucosylated proteins are recognized by calreticulin for recycling to the endoplasmic reticulum and refolding or degradation.
Synonyms: UGT2; hUGT2; UGCGL2; FLJ11485; FLJ10873; MGC150689; MGC87276; MGC117360
Tractability: Antibody: UniProt predicts a signal peptide or a membrane-spanning region. PROTAC: ubiquitination databases record sites on it; its protein half-life has been measured.
Gene: Protein-coding gene on chromosome 13 (95,801,580 to 96,053,482, reverse strand). Ensembl gene ENSG00000102595.
Subcellular location: Endoplasmic reticulum lumen; Endoplasmic reticulum- Golgi intermediate compartment
Pathways (Reactome):
Metabolism of proteins: ER Quality Control Compartment (ERQC)
Gene Ontology:
Molecular function: protein binding; UDP-glucose:glycoprotein glucosyltransferase activity
Biological process: endoplasmic reticulum mannose trimming; glycoprotein biosynthetic process; UDP-glucosylation
Cellular component: protein-containing complex; endoplasmic reticulum; endoplasmic reticulum lumen; endoplasmic reticulum quality control compartment; endoplasmic reticulum-Golgi intermediate compartment
Genetic constraint (gnomAD): Loss-of-function variants: 106 observed, 112.27 expected, observed/expected ratio (o/e) 0.94, 90% interval 0.81 to 1.11. The upper end of that interval is the gene's LOEUF score, 1.11, which puts it in group 4 of 6, group 1 being the genes least tolerant of losing a copy. Missense variants: 1,474 observed, 1,397.4 expected, observed/expected ratio (o/e) 1.05, 90% interval 1.01 to 1.1. Synonymous variants: 465 observed, 471.74 expected, observed/expected ratio (o/e) 0.99, 90% interval 0.91 to 1.06.
Homologues: Orthologues: chimpanzee UGGT2 (99% identical), macaque UGGT2 (96% identical), rabbit UGGT2 (85% identical), dog UGGT2 (84% identical), pig UGGT2 (82% identical), guinea pig UGGT2 (80% identical), mouse Uggt2 (79% identical), rat Uggt2 (78% identical), tropical clawed frog uggt2 (64% identical), zebrafish uggt2 (60% identical), Caenorhabditis elegans uggt-1 (41% identical), Drosophila melanogaster Uggt (41% identical), and 1 more. Paralogues in human: UGGT1 (55% identical).
Diseases named in the same sentence as UGGT2 in open-access papers:
UGGT2 is named in the same sentence as 12 diseases in open-access papers, as found by Europe PMC text mining. Sharing a sentence is not in itself a finding about the gene and the disease. The quoted sentences say what the papers report.
epilepsy (1 paper, 2024). A brain disorder characterized by episodes of abnormally increased neuronal discharge resulting in transient episodes of sensory or motor neurological dysfunction, or psychic dysfunction. "Surprisingly, we also identified many differential proteins such as UGGT2, SEMG1, PDIA4, ROR1, NIF3L1, and ITIH4, that have not previously been directly reported with epilepsy." (PMID 38585359, 2024).
heart failure (1 paper, 2025). Inability of the heart to pump blood at an adequate rate to meet tissue metabolic requirements. "MR analysis identified significant causal associations between the genes implicated in BW loss (ADD3, HSPA12A, SLC18A2, PDZD8, DUSP5, CASP7) as well as EF% and LV volumes (GPC6, UGGT2, SLAIN1, POU4F1, MBNL2) in BXD mice post-DOX and heart failure (HF) outcomes in humans." (PMID 40321772, 2025).
Hypertension (1 paper, 2025). The presence of chronic increased pressure in the systemic arterial system. "Several genes (CCK, SLCO1A2, UGGT2) were identified as targets of drugs (diazoxide, nadolol, hydrochlorothiazide) used to treat hypertension, suggesting opportunities for drug repositioning and risk factor prevention." (PMID 40034430, 2025).
cancer (2 papers, 2019 to 2021). A tumor composed of atypical neoplastic, often pleomorphic cells that invade other tissues. "Many of the genes such as JHY, PLAAT1, PNMA8B, RPL37P6, SNX32, UGGT2 and Y_RNA have not been related to any cancer, yet." (PMID 33672117, 2021).
UGGT2 also shares sentences with these, for which no sentence is quoted: cervical cancer (1 paper); colonic carcinoma (1); kidney stone (1); lung carcinoma (1); lysosomal storage disease (1); metachromatic leukodystrophy (1); schizophrenia (1); tumour (1).